HIF1A (hypoxia inducible factor 1 subunit alpha)
Diseases named in the same sentence as HIF1A in open-access papers (continued):
Sharing a sentence is not in itself a finding about the gene and the disease.
infection (continued). "When HIF-1α was knocked-down, NleB-enhanced cellular glucose uptake by infection with the wild-type EPEC E2348/69 strain was diminished (p = 0.1184)." (PMID 30125331, 2018). "To directly investigate how HIF1α affects macrophage polarization differentiation during different pathogen infections, we observed macrophage functional alterations in vitro." (PMID 29483608, 2018). "In macrophages it has been demonstrated that HIF-1α can be induced by immune stimuli such as LPS treatment or infection with a variety of bacterial pathogens." (PMID 29370315, 2018). "An in vitro study showed that in vitro infection with influenza H1N1 virus promotes the secretion of proinflammatory cytokines by inducing nuclear translocation of HIF‐1α." (PMID 29863786, 2018). "To abrogate HIF’s transcriptional activity, we knocked down HIF-1α by infection of lentivirus expressing short hairpin RNA for HIF-1α (shRNA, gift from Dr. Yu-Chung Yang) or control-scrambled shRNA." (PMID 29652803, 2018). "Due to the infection, an inflammation and immune response develop, and as a consequence a HIF‐1α signature is seen." (PMID 29976786, 2018). "Among Flaviviridae viruses, HCV is known to induce HIF-1α stabilization at late time points post-infection." (PMID 30513781, 2018). "We observed that after silencing HIF-1α, parasite infectivity and parasitic load were significantly (p < 0.001) reduced at 24 h of infection." (PMID 29568285, 2018). "Previously, it has been reported that after infection, several classes of pathogens such as Salmonella typhimurium, Pseudomonas aeruginosa, Streptococcus pyogenes, and HIF-1α promote killing of pathogens by modulating immune response of the host." (PMID 29568285, 2018). "We and others have shown that HIF-1α is an important mediator of host defense in macrophages, and HIF-1α deficient mice are extremely susceptible to infection with M. tuberculosis." (PMID 29370315, 2018). "The marked increase in HIF-1α levels after 6 h under hypoxia (1% O2) defined the duration of hypoxia prior to infection for the in vitro and in vivo experiments." (PMID 30082478, 2018). "Consistent with this, the nuclear localization of HIF-1α, analyzed by nucleus/cytoplasm fractionation, increased after 8 h, but then decreased at 24 h post-infection." (PMID 28401064, 2017). "About 25–30% of HIF-1α–sufficient Ly6Chi/int monocytes contained parasites after 12h of infection; at 24h, 40–45% of the cells harbored parasites." (PMID 28892492, 2017). "Consistent with this possibility, we did observe that HIF-1α silencing augmented Cyclin D1 mRNA after infection." (PMID 28401064, 2017). "Wild-type and myeloid cell–specific HIF-1α knockout mice were infected with Friend retrovirus (FV), and immune response was analysed 7 and 10 days after infection." (PMID 29222473, 2017). "CSF1R mRNA and HIF-1α target gene expression were up-regulated in the skin and down-regulated in the intestine post infection." (PMID 28542591, 2017). "In AGS cells infected by H. pylori, LY294002 (at 5 and 10 μM) reduced significantly HIF-1α induction observed 4 and 8 h post-infection (respectively)." (PMID 28401064, 2017). "Our studies showed that H. pylori-induced PI3K/Akt activation is transient, occurs relatively early on following infection and follows kinetics similar to those observed for HIF-1α induction." (PMID 28401064, 2017). "Augmentation of the activity of HIF1A or molecules within its pathway early on in the disease process have been explored as a therapeutic option for some infections, but is yet to be investigated in MK." (PMID 28573109, 2017). "Antibody‐dependent infection is augmented by hypoxia through FcγRIIA induction, through a possible activator role of HIF1α as well as HIF1α‐independent alteration in membrane ether‐linked PE levels." (PMID 28320741, 2017). "HIF-1α has been reported to be a common pathway for the infection of human oncogenic viruses including HBV, suggesting that HIF-1α regulates the overexpression of MDR1." (PMID 27999186, 2017).
infection (continued). "Curiously, however, knockdown of HIF1α and its resultant decrease in FcγRIIA expression only led to a modest decrease in infection of antibody‐opsonized DENV." (PMID 28320741, 2017). "It was shown that Hif-1α expression was increased in U937 cells as infected by H37Rv at 5 and 24 h post-infection." (PMID 28835201, 2017). "In some infection models or in vitro experiments, HIF-1α appears to be mainly expressed by M1-like macrophages and to promote pathogen clearance; while in models of chronic inflammation, HIF-1α has a more immunosuppressive role." (PMID 28892492, 2017). "During the acute phase of infection, HIF-1α impairs dendritic cell functions and limits CD8 T cell expansion." (PMID 28892492, 2017). "Concomitant with the artificial overexpression of mature miR-199a-5p by Ad-miR-199a infection, the HIF-1α protein level was significantly downregulated with miR-199a-5p though little change was observed for the level of HIF-1α mRNA." (PMID 29137361, 2017). "Although HIF-1α can protect against some infections, it appears to worsen infection with K. pneumoniae." (PMID 27624128, 2016). "In light of these results, understanding the effects of hypoxia on epithelial cells during infections offers a new potential for pharmacological interference and the use of HIF-1α as a therapeutic target." (PMID 26731748, 2016). "Hypoxia and M.tb infection synergistically drove prolonged and increased HIF-1α accumulation in MDMs compared with cells exposed to either stimulus alone, with HIF-1α accumulation detectable from 4 h after infection." (PMID 27245780, 2016). "Our data shows that IRF-5 participates in limiting antigen-specific CD8+ T cell expansion at the very early stages of infection by indirectly inducing HIF-1α expression in DCs." (PMID 26046638, 2015). "The downstream signaling of TLR involves NFκB, which plays a central role in regulating the immune response to infection and inflammation, and also induces a HIF-1α mRNA transcriptional response." (PMID 26491664, 2015). "Taken together, our data indicates that HIF-1α function in response to infection and inflammation is to restrain NF-κB activity, thus preventing excessive and harmful pro-inflammatory responses." (PMID 25510503, 2015). "Pharmacological HIF-1α activation remarkably decreased bacterial burden in the urine, bladder and kidneys compared to vehicle treated mice 18–24 h post-infection." (PMID 25927232, 2015). "We then analyzed by confocal imaging HIF-1α protein levels in lung of uninfected mice and of mice at day 30 post-infection." (PMID 26658723, 2015). "The stabilisation of Hif-1α primes neutrophils with increased NO levels, allowing the host to deal with infection better." (PMID 26512123, 2015). "When we analyzed Hif1a transcription profiles in M. tuberculosis-infected mouse lungs, we found that Hif1a mRNA levels increased 2-fold during infection." (PMID 26658723, 2015). "In conclusion, we demonstrate that IRF-5-mediated inflammation induced by L. donovani at the onset of the infection participates in limiting CD8+ T cell expansion by upregulating HIF-1α in DCs and subsequently impairing DC functions." (PMID 26046638, 2015). "Because only a very small percentage of splenic DCs bury parasites during acute infection, accumulation of HIF-1α mRNA in DCs is most likely due to the inflammatory milieu induced by IRF5." (PMID 26046638, 2015). "AKB-4924 treated animals had an approximately 2-fold increase in HIF-1α mRNA recovered from their bladders upon infection." (PMID 25927232, 2015). "The downregulation of HIF-1α during MRV infection of PCa cells is mediated by proteasome-mediated degradation, and translational inhibition." (PMID 24504474, 2014). "In the present study, there was a significant reduction in the infection-induced up-regulation of HIF1α when mice were treated with Cl2MDP-loaded liposomes, indicating that the source of increase in transcripts was attributable to the influx of macrophages." (PMID 24465430, 2014).
infection (continued). "Considering that transgenic expression of CXCL1 during the course of infection improved fungal burden and survival during infection with A. fumigatus, understanding the exact mechanism for HIF1α regulation of CXCL1 is of great importance." (PMID 25255025, 2014). "Hypoxia inducible factor 1α (HIF-1α) stabilization was shown to be involved in leukocyte activation and host defense in murine and zebrafish models of inflammation and infection." (PMID 24967596, 2014). "Previous reports have identified a role for HIF1α in tissue adhesion, migration and invasion by neutrophils and macrophages at sites of infection and inflammation." (PMID 25255025, 2014). "Surprisingly, the addition of MG132 at later times in infection was unable to rescue HIF-1α, suggesting that, in addition to proteasome-mediated degradation, a second mode of inhibition of HIF-1α protein accumulation was occurring in MRV infected cells." (PMID 24504474, 2014). "We identified an optimal cell surface oxygen level for maximizing infection and demonstrate that host HIF-1α is at least partially responsible for this response." (PMID 24291761, 2014). "Our previous data indicate that Mm are more susceptible to increased host nitrosative defenses at early stages of infection when induced by stabilized Hif-1α, before they have the opportunity to sense and manipulate the host immune response." (PMID 24967596, 2014). "miR-210 abundance was enhanced in HIF-1α-dependent manner following parasite infection in human primary macrophages." (PMID 24790587, 2014). "The antimicrobial effect of Hif-1α stabilization, and Hif-2α reduction, were demonstrated to be dependent on inducible nitric oxide synthase (iNOS) signaling at early stages of infection." (PMID 24367256, 2013). "Using a well-established zebrafish/Mm infection model of TB, we have identified a new anti-mycobacterial leukocyte phenotype being driven by Hif-1α stabilization and consequent iNOS activity." (PMID 24367256, 2013). "Increasing Hif-1α signaling enhanced levels of reactive nitrogen species (RNS) in neutrophils prior to infection and was able to reduce larval mycobacterial burden." (PMID 24367256, 2013). "Stabilization of Hif-1α, or reduction of Hif-2α, results in priming of neutrophil NO bactericidal activity leading to lower mycobacterial burden after challenge with infection." (PMID 24367256, 2013). "In extension of these findings, the authors pursued the role of bacterial siderophores in HIF1A activation during infection with Enterobacteriaceae." (PMID 24086109, 2013). "Upregulation and stabilization of HIF-1α is a known consequence of leukocyte activation during onset of infection, even in normoxia, and remains high during pathogenesis of other types of bacterial infections leading to enhanced leukocyte function." (PMID 24367256, 2013). "Cells were collected after 5 days of activation/infection, and the levels of HIF1A and prolylhydroxylases 1 and 2 were compared in NiCl2-treated and -untreated cells." (PMID 22848707, 2012). "IκB kinase (IKK)-β-dependent activation of NF-κB stimulates HIF-1α transcription following infection of macrophages with group A Streptococcus or P. aeruginosa, as a mechanism to stimulate the production of HIF-induced anti-microbial peptides." (PMID 22094132, 2012). "After 6 h of infection, J774 cells were treated with cycloheximide (5 μg/ml) and rate of HIF-1α degradation was analyzed by Western blot analysis." (PMID 22701652, 2012). "A steady increase up to about 4-fold in HIF-1α protein level was detected with increased multiplicity of infection of LD." (PMID 22701652, 2012). "About 2 fold increase in luciferase activity by LD infection confirmed the involvement of HIF-1α transcription for HIF-1 activation in host macrophage." (PMID 22701652, 2012). "It is quite likely that hypoxia and inflammation act synergistically to increase the level of HIF-1α in this infection, as it has in other models of infection in mice." (PMID 23006927, 2012).
infection (continued). "To confirm the involvement of transcriptional mechanism, we cloned HIF-1α promoter in pGL3-basic vector upstream of luciferase gene, transfected into cells and performed luciferase assay after LD infection or LPS treatment." (PMID 22701652, 2012). "Immunoblotting reslults showed that Ad-siHIF-1α infection greatly blocked HIF-1α expression when compared to the Ad-GFP treatment at protein level, but did not affect AKT and ERK1/2 activation, confirming that HIF-1α is the downstream molecule of AKT and ERK." (PMID 21544242, 2011). "We are currently exploring the role that K5 plays in this upregulation of HIF-1α during infection using viruses deleted for K5." (PMID 21490960, 2011). "To ensure that pORF3 expressed from infection with recombinant adenoviruses was functionally similar to that expressed following plasmid transfection, we checked its effects on HIF-1α and Akt." (PMID 21799848, 2011). "C. pneumoniae has an additive effect on hypoxia-inducible factor-1 alpha (HIF-1α) stabilization resulting in enhanced glucose uptake of Hep-2 cells during the early phase of infection." (PMID 20485672, 2010). "While some studies have identified a host-protective role of HIF-1α during inflammation or infections, other studies have found a contribution of HIF-1α activation in growth and survival of human pathogens." (PMID 18839041, 2008). "In fact, previous studies have revealed that HIF-1α can be stabilized during infections with human pathogens via oxygen-dependent or oxygen independent pathways." (PMID 18839041, 2008). "Taken together, these studies suggest a functional role of HIF-1 α in transcriptional induction of HIF-1α -targeted genes during infection with RSV." (PMID 18839041, 2008). "Taking together, these studies suggest hypoxia-independent activation of HIF-1α during infection with RSV in vitro and in vivo." (PMID 18839041, 2008). "In contrast, induction of HIF-1α target genes was completely abolished after similar infection doses with UV-inactivated RSV." (PMID 18839041, 2008). "Previous studies of HIF-1α during inflammation and infection have found oxygen-independent activation of HIF-1α during infections with human pathogens." (PMID 18839041, 2008). "Taken together, these studies reveal robust stabilization of HIF-1α during infection with life RSV in vitro." (PMID 18839041, 2008). "Other studies have identified a crosstalk between viral genes and the HIF-1α pathway during infections with the human herpesvirus 8 (HHV-8)." (PMID 18839041, 2008). "At the indicated time points after infection, mice were anesthetized, lungs were shockfrozen and HIF-1α was determined by Western blot analysis." (PMID 18839041, 2008). "For example, a recent study on molecular mechanisms of how bacteria activate HIF-1α found a role of bacterial siderophores in HIF-1α activation during infection with Enterobacteriaceae." (PMID 18839041, 2008). "Other studies found HIF-1α stabilization during hepatitis B infections or during infections with the Eppstein-Barr virus." (PMID 18839041, 2008). "In the present studies we pursued HIF-1α stabilization and gene-transcription during infection with RSV–one of the most potent biological stimuli to induce an inflammatory milieu." (PMID 18839041, 2008). "Notably, we found that PRC2-mediated heterochromatin inhibits the HIF-1α-mediated upregulation of lytic genes as chromatinization of the KSHV genome progresses during infection." (PMID 41805195, 2026). "Additionally, we found that HIF-1α induces lytic de novo infection only if expressed within the first 24 h post-infection (hpi)." (PMID 41805195, 2026). "Moreover, Lj-EVs were associated with metabolic alterations, characterized by enhanced oxidative phosphorylation during homeostasis and suppression of HIF-1α-mediated glycolysis during infection." (PMID 42057229, 2026).
infection (continued). "After infection, the influx of immune cells and altered blood flow result in local hypoxia, a stimulus that stabilizes the transcription factor hypoxia-inducible factor-1α (HIF-1α)." (PMID 40590226, 2025). "Vaccinia virus (VACV) infection causes stabilization and subsequent activation of HIF1α even under normoxic conditions, resulting from VACV protein C16 binding to PHD2 and inhibiting PHD2-mediated hydroxylation of HIF1α." (PMID 39601573, 2025). "Based on the importance of the glycolysis–HIF-1α–inflammation axis in infection and M. bovis’s reliance on glycolysis, this study specifically aimed to Identify and characterize the interaction between M. bovis ENO1 and host cell proteins, focusing on ACTB and its critical binding sites." (PMID 40867552, 2025). "This short infection period did demonstrate the anticipated macrophage control of the intracellular bacteria through up-regulation of complement, Aif1, Maf, and pathway enrichment of oxidative stress, phagosome formation, and HIF-1α signaling." (PMID 39813329, 2025). "In contrast, macrophages in moderately hypoxic regions of the same lesion may benefit from iNOS expression induced by HIF-1α stabilization, with sufficient molecular oxygen available to sustain NO production and effectively control the infection." (PMID 40512023, 2025). "The glycolysis–HIF-1α–inflammation signaling axis plays a critical role in pathogen infection." (PMID 40867552, 2025). "HIF-1α upregulation observed might be attributed to ROS produced by the cell during the gemykibivirus infection." (PMID 41157602, 2025). "However, myeloid-specific HIF-1α-/- mice infected with L. donovani and humans with a loss-of-function HIF1A gene polymorphism are more susceptible to infection." (PMID 40191198, 2025). "The elevated levels of HIF-1α and HIF-2α could reflect the body’s attempt to adapt to the hypoxic conditions in the gastric mucosa caused by the infection." (PMID 40731804, 2025). "Since SVCV infection stabilizes hif1α proteins and induces hypoxia response in zebrafish, we sought to know whether inhibiting hif1α could modulate antiviral response." (PMID 39601573, 2025). "Of note, the ‘HIF-1α signaling pathway’ was upregulated with infection." (PMID 40191198, 2025). "Given that glycolysis is driven by HIF1α, we investigated the role of glycolysis during infection." (PMID 40387431, 2025). "The impact of HIF-1α activation during infections remains unclear, with uncertainty surrounding whether it has a protective or harmful effect on the host." (PMID 40731804, 2025). "HIF1α-depleted monocytes also showed a similar response to the infection." (PMID 40570045, 2025). "The latent nuclear antigen (LANA) encoded by ORF73, which is expressed during the latent phase of infection, forms a complex with HIF-1α and recruits chromatin remodeling enzyme KAP1 to the RTA promoter region, further regulating the initiation of lytic replication." (PMID 40443737, 2025). "Hypoxia also plays a role in SARS-CoV-2 infection; HIF-1α accumulates in the lung epithelia after infection, and due to its role as a transcription factor for pro-inflammatory cytokines, it may play a role in the lung damage seen after SARS-CoV-2 infection." (PMID 39203555, 2024). "Furthermore, the upregulation of HIF-1α in macrophages contributes to the clearance of infections by enhancing bactericidal effects against pathogens such as mycobacterium tuberculosis." (PMID 39575238, 2024). "Thus, keratinocytes can respond to infections by activating the HIF-1α cascade to increase glucose uptake and subsequent glycolysis utilization, generating energy to fight the infection." (PMID 38248981, 2024). "As expected, treatment of AECs with LW6 (20 μM) prevented infection-induced accumulation of HIF1α." (PMID 38902255, 2024). "On the one hand, nurturing HIF1A-mediated glycolytic activity in DCs during the early stages of infection could potentially enhance the effectiveness of preventive strategies for TB." (PMID 38922679, 2024).